CCDC166 (coiled-coil domain containing 166)
Tractability: No criterion of Open Targets' tractability assessment is met for any kind of drug.
Gene: Protein-coding gene on chromosome 8 (143,706,694 to 143,708,109, reverse strand). Ensembl gene ENSG00000255181.
Genetic constraint (gnomAD): Loss-of-function variants: 17 observed, 10.74 expected, observed/expected ratio (o/e) 1.58, 90% interval 1.05 to 1.94. The synonymous counts are far from expectation, so gnomAD's model fits this gene poorly and the ratio says little. Missense variants: 738 observed, 555.24 expected, observed/expected ratio (o/e) 1.33, 90% interval 1.25 to 1.41. Synonymous variants: 336 observed, 263.56 expected, observed/expected ratio (o/e) 1.27, 90% interval 1.16 to 1.39.
Homologues: Orthologues: chimpanzee CCDC166 (98% identical), macaque CCDC166 (94% identical), rabbit CCDC166 (69% identical), guinea pig CCDC166 (67% identical), rat Ccdc166 (59% identical), dog CCDC166 (34% identical), tropical clawed frog ccdc166 (24% identical). Paralogues in human: BBOF1 (15% identical).
Diseases named in the same sentence as CCDC166 in open-access papers:
CCDC166 is named in the same sentence as 4 diseases in open-access papers, as found by Europe PMC text mining. Sharing a sentence is not in itself a finding about the gene and the disease. The quoted sentences say what the papers report.
breast carcinoma (1 paper, 2022). "To examine the clinical significance of CanCord34 overexpression in breast cancer patients, next, we performed a multivariate analysis of the CanCord34 genes using the Kaplan–Meier survival program, for which clinical data were available, except for data on CCDC166." (PMID 36497066, 2022).
signet ring cell carcinoma (1 paper, 2022). A usually aggressive, poorly differentiated invasive adenocarcinoma characterized by the presence of malignant glandular cells in which the nucleus is pressed to one side by the presence of intracytoplasmic mucus. "CCDC166 was found to be highly mutated in signet ring cell carcinoma." (PMID 35115040, 2022).
cancer (1 paper, 2022). A tumor composed of atypical neoplastic, often pleomorphic cells that invade other tissues. "Furthermore, three of the CanCord34 genes, namely MROH6, ZNF623, and CCDC166, have no prior PubMed publications in the context of cancer." (PMID 36497066, 2022).
tumor (1 paper, 2022). "In general, we found a higher expression of CanCord34 genes in the differentiated tumor cells, except for CCDC166, GSDMD, TSTA3, and highly purified BCSCs cells, compared to the other stem cell types." (PMID 36497066, 2022).